RNU6-273P (RNA, U6 small nuclear 273, pseudogene)
Gene: Small nuclear RNA gene on chromosome 14 (37,187,219 to 37,187,314, forward strand). Ensembl gene ENSG00000252746.
Homologues: Orthologues: chimpanzee U6 (98% identical), macaque U6 (92% identical), rabbit U6 (69% identical), mouse Gm22165 (67% identical), mouse Gm26479 (60% identical), rat LOC120099054 (60% identical). Paralogues in human: RNU6-1099P (86% identical), RNU6-28P (86% identical), RNU6-43P (86% identical), RNU6-560P (86% identical), RNU6-1020P (85% identical), RNU6-11P (85% identical), RNU6-1329P (85% identical), RNU6-222P (85% identical), RNU6-37P (85% identical), RNU6-454P (85% identical), RNU6-774P (85% identical), RNU6-86P (85% identical), and 1285 more.